MADCAM1 (mucosal vascular addressin cell adhesion molecule 1)
Diseases named in the same sentence as MADCAM1 in open-access papers (continued):
Sharing a sentence is not in itself a finding about the gene and the disease.
fibrosarcoma (1 paper, 2017). A malignant mesenchymal fibroblastic neoplasm affecting the soft tissue and bone. "Expression of LIGHT in a fibrosarcoma cell line resulted in upregulation of CCL21 and MAdCAM-1 on tumor vasculature, facilitating recruitment of vast numbers of naive CD8+ T lymphocytes, which appeared to then be sufficiently activated in situ to facilitate rejection of established tumors." (PMID 29312327, 2017). "Similarly, the expression of LIGHT in a fibrosarcoma cell line resulted in upregulation of CCL21 and MAdCAM-1, facilitating the recruitment of vast numbers of naive CD8+ T lymphocytes, which were then sufficiently activated in situ to facilitate rejection of established tumors." (PMID 29312327, 2017).
fibrosis (1 paper, 2024). the formation of excess fibrous connective tissue in an organ or tissue in a reparative or reactive process. "In this study, we report the involvement of the α4β7/MAdCAM-1 axis in the recruitment of α4β7+ T cells to the fibrotic liver, highlighting their pivotal role in promoting hepatic fibrosis progression." (PMID 38727292, 2024).
HIV-1 infection (1 paper, 2022). The type species of lentivirus and the etiologic agent of acquired immunodeficiency syndrome (AIDS). "HIV-1 virions incorporate integrin α4β7 and can be captured by MAdCAM-1-expressing cells, facilitating HIV-1 infection." (PMID 35758666, 2022).
inflammatory skin disease (1 paper, 2021). Inflammatory skin disorders covers a broad category that includes many conditions ranging in severity, from mild itching to grave medical health complications These disorders are common in people of all ages and races. "They reported MAdCAM-1 overexpression in IBD but not in inflammatory skin diseases." (PMID 34827121, 2021).
liver disease (1 paper, 2007). "This system may provide a useful model for studying inflammatory mechanisms in liver disease and help determine if controlled MAdCAM-1 expression might influence inflammation in liver disease." (PMID 17868448, 2007).
liver failure (1 paper, 2025). A liver disease characterized by the liver losing or has lost all of its function. "Similarly, serum MAdCAM-1 levels appeared to be significantly elevated in patients with liver failure and were suggested to be a promising early predictor of liver failure." (PMID 41301753, 2025).
lymphoma (1 paper, 2015). A malignant (clonal) proliferation of B- lymphocytes or T- lymphocytes which involves the lymph nodes, bone marrow and/or extranodal sites. "Madcam1 is overexpressed in pancreatic tumor and lymphoma, suggesting that Madcam1 plays a critical role in tumorigenesis." (PMID 26124182, 2015).
metastatic tumors (1 paper, 2023). "In the present study, we did not identify any mutations in the MADCAM1 gene in either the primary or metastatic tumors." (PMID 37422528, 2023).
non-alcoholic steatohepatitis (1 paper, 2024). "Our results align with previous studies that reported protective effects against diet-induced non-alcoholic steatohepatitis (NASH) in mice lacking whole-body expression of MAdCAM-1 or treated with α4β7 or MAdCAM-1 mAbs." (PMID 38727292, 2024).
obstructive jaundice (1 paper, 2017). A finding indicating increased bilirubin levels in the blood and urine, due to intrahepatic or extrahepatic obstruction of the biliary system. "According to animal studies, obstructive jaundice downregulates the numbers of CD4+ and CD8+ T-lymphocytes and MAdCAM-1 expression in the lamina propria." (PMID 29209365, 2017).
Onset (1 paper, 2022). The age group in which disease manifestations appear. "In a study from our centre of adolescent participants with early-onset psychosis, reduced levels of PSEL and VCAM-1 and no significant alterations of ICAM-1, MadCAM-1, JAMA or NCAD, were found." (PMID 35856063, 2022).
peritonitis (1 paper, 2023). Inflammation of the peritoneum (tissue that lines the abdominal wall and covers most of the organs in the abdomen). "However, it cannot be excluded that eosinophils rely on other molecules besides VCAM-1, such as MAdCAM-1, to adhere to endothelium in the thioglycolate-induced peritonitis model." (PMID 36756125, 2023).
renal fibrosis (1 paper, 2016). A final common manifestation of a wide variety of chronic kidney diseases characterized by glomerulosclerosis and tubulointerstitial fibrosis. "The list of genes includes Fblim1, Epha2, Wisp1, Parvg, Madcam1, Mybpc2, Cdh3, Gpr56, Troap, Pstpip1, Pcdh8, Nlgn2 and Mfap4, genes that based on Pubmed and Kidney and Urinary Pathway Knowledge Base12 searches have not been previously associated with renal fibrosis." (PMID 27189340, 2016).
sinusitis (1 paper, 2016). An acute or chronic inflammatory process affecting the mucous membranes of any sinus cavity. "Even though the main ligand for α4β7, the intestinal MadCAM-1, is reported to be expressed also on venules of the URT, only 24% (in sinusitis) and 15% (in tonsillitis) of the URT-originating plasmablasts expressed α4β7." (PMID 27128095, 2016).
steatosis (1 paper, 2020). Increased lipid within the cytoplasm of cells. "MAdCAM-1 showed a comparable expression pattern than CD62L with significantly lower expression in steatosis patients compared to the NASH group, especially when the amount of fat is <30%." (PMID 32365632, 2020).
uveitis (1 paper, 2022). An inflammatory process affecting a part of or the entire uvea. "In addition to Madcam1 upregulation, we observed T-cell infiltration in our AAV-TNF-α driven uveitis-like model, in line with well-described role for T-cells in uveitis patients and uveitis rodent models." (PMID 36371417, 2022).
tumor (30 papers, 2012 to 2025). "IHC assays showed that M2 macrophage marker CD163 in infiltrating immune cells and MADCAM1 in the tumor cells was significantly positively stained in GC samples carrying mutated MADCAM1." (PMID 35449126, 2022). "The tumor-associated mucosa had a decrease in MAdCAM-1+ and increase in PNAd+ blood vessels compared to in the unaffected mucosa and also increased production of the CCR4 ligand CCL17." (PMID 22319577, 2012). "Furthermore, the study showed that MADCAM1 mutation promotes cancer cell migration and triggers tumor metastasis by establishing an immune-suppressive microenvironment." (PMID 37422528, 2023). "Downregulation of MAdCAM-1 promotes trafficking of these immunosuppressive Treg17 cells from the gut to the tumor microenvironment, as demonstrated in murine models." (PMID 41294692, 2025). "ACS treatment induces gut dysbiosis, reduces MADCAM-1 expression in the ileum, and increases tumor infiltrating regulatory T17 cells." (PMID 39895632, 2025). "Restoration of gut MAdCAM-1, either by microbial or molecular intervention, preserves local Treg populations, reduces tumor infiltration, and enhances the efficacy of immune checkpoint inhibitors in preclinical models." (PMID 41472726, 2025). "In contrast, Venous‐1 cell subsets express the specific endothelial cell genes IL‐33, MADCAM1, SELP, and SELE, which are closely associated with leukocyte adhesion, angiogenesis, and tumor progression." (PMID 40860436, 2025). "Ectopic expression of MAdCAM-1 in mouse liver reduces the accumulation of α4β7+ Treg17 cells at tumor, thereby improving the therapeutic efficacy of immunotherapy." (PMID 41301753, 2025). "For example, Enterocloster spp can modulate the migration of immunosuppressive T cell subsets into tumors via downregulation of MAdCAM-1 where they suppress anti-tumor immunity and promote resistance to immunotherapy." (PMID 41472726, 2025). "TECs upregulate mucosal addressin cell adhesion molecule 1 (MAdCAM1), which interacts with β7 integrin expressed on Tregs, thereby preferentially promoting Treg infiltration into tumor sites." (PMID 38726320, 2024). "Dysbiosis can modulate biliary salt composition, leading to a downregulation of MAdCAM-1 and the exodus of immunosuppressive enterotropic T cells promoting tumor growth." (PMID 38395948, 2024). "As a member of the immunoglobulin family involving in lymphocyte adhesion, the roles of MADCAM1 mutants in tumor metastasis were firstly reported." (PMID 35449126, 2022). "Independent knockdown of MMP9 and Madcam1 in B16-F10 cells impeded epithelial-mesenchymal transition and inhibited subcutaneous tumor growth and formation of metastatic lung nodules in vivo." (PMID 31600735, 2019). "TNF-α can also stimulate the transcription of genes encoding endothelial cell adhesion molecules, including E selectin, ICAM-1, VCAM-1, and Madcam1, which are closely related to tumor metastasis and angiogenesis." (PMID 31600735, 2019). "To assess the effects of MMP-9 and Madcam1 deletion on tumor growth in vivo, we subcutaneously injected B16-F10 cells transfected with shRNA-MMP-9, shRNA-Madcam1, or scrambled control-shRNA into WT or TRIM59-CKO mice." (PMID 31600735, 2019). "Both immunohistochemistry and qRT-PCR confirmed decreased MMP-9 and Madcam1 expression in tumor samples derived from cells in which MMP9 or Madcam1 were knocked down." (PMID 31600735, 2019). "Taken together, these results suggest that TNF-α production by TRIM59-/--M2 macrophages promotes the expression of MMP-9 and Madcam1 in B16-F0 and B16-F10 tumor cells, enhancing their metastatic potential." (PMID 31600735, 2019). "Real time PCR demonstrated that MAdCAM-1 expression was significantly reduced in the tumor compared to the unaffected tissue." (PMID 22319577, 2012).
tumor (continued). "Another significant discovery involves Enterocloster species-mediated regulation of gut-tumor immune cell trafficking, where microbial modulation of bile acid metabolism leads to downregulation of mucosal addressin cell adhesion molecule-1 (MAdCAM-1) expression in the ileum." (PMID 40909921, 2025). "The roles of MADCAM1 mutants in tumor metastasis is a novel interesting funding." (PMID 35449126, 2022). "Here, we found that MADCAM1 mutants could not only directly promote tumor metastasis, but also could trigger tumor metastasis by establishing complicated immunosuppressive microenvironment." (PMID 35449126, 2022). "As OAC is underpinned by inflammation, this suggests the increases in α4β7 expressing cells may be mediated by increased expression of MAdCAM-1 facilitating entry in to the inflamed omentum and tumour." (PMID 35008227, 2021). "Remarkably, increased expression of multiple cell surface proteins implicated in homing and cell motility was detected in the tumour cells, including integrins such as LFA-1 (CD11a), VLA-4 (CD49d) and MAC-1 (CD11b), and adhesion molecules such as MadCAM-1, ICAM-1 (CD54) and L-selectin (CD62L)." (PMID 27297662, 2016). "Similarly, in xenograft mouse models, we found that only Madcam1 knockdown could lead to impaired tumor growth from Bel-7402 cells in vivo." (PMID 26124182, 2015). "This increase in T17 regulatory cells in the tumors either by anti-MadCam1 or anti-α4β7 blocks response to anti–PD-1 treatment in MCA205 and 4T1 mouse tumor models." (PMID 39895632, 2025). "This reduction in MAdCAM-1 decreases gut retention of immunosuppressive α4β7 + CD4 + regulatory T cells (Treg17), promoting their migration to tumor sites and consequently influencing PD-1 immunotherapy efficacy." (PMID 40909921, 2025). "Notably, administration of antibiotics resulted in down-regulation of MAdCAM-1 expression levels in the ileum, PPs and MLN, while Treg17 cells migrated out of the ileum to extra-intestinal tumor as well as to tumor-draining lymph nodes." (PMID 41301753, 2025). "The de novo programmed venular ECs, marked by MAdCAM1 that is not expressed in control mice but induced by iCoup, can be observed in the tumor nests, peritumoral regions, and the stromal area distant from malignant cell-enriched regions." (PMID 40796746, 2025). "Through the down-regulation of mucosal addressin cell adhesion molecule 1 (MAdCAM-1) in the ileum, post-antibiotic (ABX) gut recolonization by Enterocloster species facilitated the migration of enterotropic α4β7CD4 regulatory T 17 cells towards the tumor." (PMID 38074650, 2023). "Although not explored further, a likely explanation is induction of MAdCAM-1 on HEV in peripheral LN of tumor bearing mice, which occurs in immunized mice." (PMID 31249570, 2019). "Similarly, after co-incubation with PLIGHT- or PαCD3&LIGHT-transfected tumor cells, the mRNA levels of chemokines and vascular adhesion molecules in vascular endothelial cells, such as CXCL-2, CXCL-8, CXCL-12, CCL-21, MADCAM-1, and VCAM-1, rose by about 2- to 5-fold." (PMID 41406950, 2025). "MADCAM1 was reported to be highly expressed in gastrointestinal mucosal endothelium and plays a role in leukocyte traffic into the mucosal immune compartment and the roles of MADCAM1 mutants in tumor metastasis had never been reported before." (PMID 35449126, 2022).
infection (13 papers, 2012 to 2025). The state of being infected such as from the introduction of a foreign agent such as serum, vaccine, antigenic substance or organism. "To investigate if the trend for increased infection in picDC-T cell co-cultures was similarly associated with a mucosal DC phenotype, we measured the expression on dsRNA-matured DCs of MAdCAM-1, α4β7, and another mucosal homing integrin, CD103." (PMID 27603520, 2016). "STm infection induced a noticeable expansion of MadCAM-1+ cells from 7 days up to 28 days after the infection, and these cells were detected not only in the MZ but also in the follicles, and some were positive for Mfge-8." (PMID 36950118, 2023). "The capacity of vedolizumab, β7 Ab and a MAdCAM-1 Ab to suppress the differentiation of TRM-like cells necessarily reduced infection." (PMID 36897929, 2023). "We find that MAdCAM-1 + RA costimulated cells support infection, and the subsequent addition of TGF-β drives the cells to adopt a TRM-like cell phenotype." (PMID 36897929, 2023). "It is unclear why MAdCAM-1 is superior to either VCAM-1 or CD28 Ab with respect to supporting infection." (PMID 36897929, 2023). "Following infection with T. muris, a significant increase in the number of MAdCAM-1 expressing cells was observed in the large intestine of both ΔdblGATA-1 and BALB/c mice (Two-way ANOVA showed a significant effect of infection F = 9.413, p = 0.0050)." (PMID 27245920, 2016). "We recently showed that DCs imprinted with a semi-mature mucosal-like phenotype upon retinoic acid (RA) conditioning drive infection in DC-T cell co-cultures in a manner involving MAdCAM-1, the natural ligand for the gut homing integrin, α4β7." (PMID 27603520, 2016). "Both MAdCAM-1 and CCL25 have previously been suggested to be important in the recruitment of plasma cells to the intestine; therefore the expression of these molecules in eosinophil-deficient and control mice post-infection was analysed." (PMID 27245920, 2016). "Because leukocyte homing is required for the generation and maintenance of immune responses against pathogens, we speculate that suppression of Madcam1 by a specific inhibitor may lead to an impaired immune response to infection." (PMID 26124182, 2015). "Therefore, MadCAM-1+ cells and perivascular PDGFRβ+ cells expand during STm infection." (PMID 36950118, 2023). "While CD28 Ab, VCAM-1 and MAdCAM-1 all promoted the formation of TRM-like cells, only MAdCAM-1 + RA costimulation consistently supported infection." (PMID 36897929, 2023). "There was a higher level of integrin α4β7 on CD3+ T cells after infection by PEDV, and the expression of MAdCAM-1 in sow colostrum was increased after oral infection with PEDV." (PMID 35758666, 2022). "We suggested that the combination of MAdCAM-1 and RA, which is primarily localized to GALT and genital mucosa, might contribute to the gut-tropic nature of HIV in the acute phase of infection." (PMID 36897929, 2023). "Infection induced changes in adhesion molecule expression were not global, as MAdCAM-1+ BECs were not different in WT or TRPV1-/- mice." (PMID 38109366, 2023). "In contrast, at day 21 after infection, most CXCL13 is associated with MadCAM-1+ cells, which are distributed throughout the WP and are not restricted to the marginal sinus." (PMID 36950118, 2023). "In contrast, following infection with T. gondii no significant changes in MAdCAM-1 expression was observed in the small intestine (Two-way ANOVA, effect of infection p = NS)." (PMID 27245920, 2016). "Additionally, these cells do not support infection in the same manner as MAdCAM-1." (PMID 36897929, 2023). "Alongside these effects after infection, mature FDC networks are strikingly absent, whereas immature FDC precursors, including marginal sinus pre-FDCs (MadCAM-1+) and perivascular pre-FDCs (PDGFRβ+) are enriched." (PMID 36950118, 2023).
cancer (10 papers, 2012 to 2025). A tumor composed of atypical neoplastic, often pleomorphic cells that invade other tissues. "However, further studies are needed, as disruption to the α4β7/MAdCAM-1 axis has been associated with reduced anti–PD-1 efficacy during cancer therapy." (PMID 39903521, 2025). "For example, we have demonstrated that soluble MAdCAM-1 (sMAdCAM-1), measured via a Luminex assay, correlated with ileal transcripts and the clinical prognosis of cancer patients." (PMID 40305219, 2025). "Indeed, multiple courses of ATB further downregulate MAdCAM-1 in patients with cancer undergoing ICI treatment." (PMID 40305219, 2025). "Moreover, the higher expression levels of certain TSGs, including GSTA2, CCL21, and MADCAM1, were associated with a significantly higher ITR in cancer." (PMID 32774369, 2020). "Therefore, 6 of the genes (ENC1, ACAT1, MSTC1, MADCAM1, RPL23 and SNRPB2) were found to be associated with cancer, genetic disorder or reproductive system disease within the same network." (PMID 22280244, 2012). "Previous studies also showed that the expression of certain TSGs could promote antitumor immunity in diverse cancers, such as CCL21, MADCAM1, and FCER2." (PMID 32774369, 2020). "Cancer cells of growing ribociclib-resistant tumors used a diverse set of M2-like differentiation stimulating communication pathways as shown by a range of markers: CSF1, CLCF1, several FGFs (1/2/7/17/18/23), the TGF family member GDF9, interleukin 5/11/12, MADCAM1 and PLAU." (PMID 40032842, 2025).
genetic disorder (2 papers, 2012 to 2020). "NKX2‐3 has hitherto not been linked to a genetic disorder but the gene is a strong candidate gene for intestinal varices as it is expressed in human intestinal microvascular cells where it regulates VEGFA and MADCAM‐1 signalling." (PMID 31498527, 2020).
inflammation (1 paper, 2024). Aberrant reaction of the microcirculation characterized by movement of fluid and leukocytes from the blood into extravascular tissues. "MAdCAM-1 expression is increased at sites of intestinal inflammation, and MAdCAM-1 is also expressed at extra-intestinal sites that can be affected in patients with IBD, such as the joints, eyes, and skin." (PMID 37556361, 2024).
retinopathies (1 paper, 2022). "Remarkably, TNF-α stimulation strongly increased Madcam1 expression in HRMECs, suggesting that MAdCAM-1 may play an important role also in the human retina and may contribute to disease progression of various human retinopathies." (PMID 36371417, 2022). "Thus, to test whether MAdCAM-1 may also be relevant for human retinopathies, we stimulated primary human retinal microvascular endothelial cells (HRMEC) with recombinant, human TNF-α." (PMID 36371417, 2022).